CD4 (CD4 molecule)
Diseases named in the same sentence as CD4 in open-access papers (continued):
Sharing a sentence is not in itself a finding about the gene and the disease.
infection (continued). "In addition, a comparison of the decrease in CD4 + T cell levels before and after infection showed that the Mo/Se group had a significantly greater decrease in CD4 + T cell levels than those in the mild disease group." (PMID 38172680, 2024). "CD4 T cell polyfunctionality index was lowest in Bhlhe40-/- mice and highest in Il10-/- mice, and these indices reversely correlated with bacterial shedding over the course of C. muridarum primary infection." (PMID 38271477, 2024). "In the general population, compared to non-severe cases, severe infection was associated with lower lymphocyte counts, increased CD4+ and CD8+ Tem, and relative preservation of Treg over Th1/Th17 cells." (PMID 38500883, 2024). "However, at later stages of infection, CD4+ T cells in the crypts emerge as the major sources of IL-22, as demonstrated by studies using CD4CreIl22flox/flox mice, which specifically lack Il22 in T cells." (PMID 39379604, 2024). "Other studies have assessed HIV-1 trans-infection into CD4+ T cells in alternative cellular models with limited CD169 expression, indicating that other host factors may be relevant during the process." (PMID 39867902, 2024). "However, chronicMtb infection such as a latent TB infection is known to elicit effectormemory phenotype in CD4+ and CD8+ T cells." (PMID 39257997, 2024). "Different lymphocytes produce IFN© within this immune organ, including NK and CD8+ T cells, traditionally associated with IFN© production during Tg infection, as well as NKT, ©δ and CD4+ T cell more recently implicated in the inflammatory response to Tg infection." (PMID 38950025, 2024). "Given their importance, we examined whether BA.5 breakthrough infection could quickly recall and expand ancestral- and BA.5-specific CD4+ and CD8+ T cell responses." (PMID 38456703, 2024). "Moreover, this process of cell-to-cell virus spreading is efficient for the productive ex vivo infection of purified primary tissue macrophages from various origins by fusion with infected CD4+ T cells." (PMID 38400063, 2024). "CD8+ and CD4+ T cells play pivotal roles in the human adaptive immune response against influenza infection, and persistent alterations in their function and subset composition following infection have significant implications for long-term prognosis." (PMID 39129565, 2024). "Furthermore, due to distinctive features of the pathogenesis of M. tuberculosis infection, both a CD8+ T-cell response and a CD4+ T-cell response are necessary in the initial phases of the infection; they can be successfully induced by ESAT6-based vaccines." (PMID 39591170, 2024). "Consequently, we concentrated on the HIV-1 T/F strain CH077.t, which consistently showed detectable infection in CD4+ T cells, to assess its response to semen and bNAbs." (PMID 38501840, 2024). "CD4+ T cell responses to N peptides were detected also in some participants before the infection (N=11), but the activation levels were significantly lower compared to the levels seen after a breakthrough infection (p<0.0001 at 3D3mo, p=0.0005 at 3D8-12mo, p=0.0001 at 4D3wk, and p=0.0498 at 4D3mo)." (PMID 39640263, 2024). "The balance between CD4+ Th1 and Th2 cells is also important during infection." (PMID 38216639, 2024). "This CD4/CD8 imbalance, seen in response to natural infection and vaccination, might be due to the inactivated nature of CoronaVac® and the aluminum hydroxide adjuvant favoring CD4+ over CD8+ T-cell." (PMID 39763646, 2024). "In addition, the proportion of IFN-γ-producing CD4+ Th1 cells showed similar kinetics to the IFN-γ concentration during infection." (PMID 38969796, 2024). "Interestingly, the naïve CD4+ T cell population was higher in coinfected patients compared to the HIV single infection group, while the opposite pattern was observed in Tregs." (PMID 39204027, 2024).
infection (continued). "Concomitant with these changes in antigen specificity, diverse poly-functional subtypes have been reported to emerge with time from primary infection, affecting cytokine production of CD4+ and CT8+ T cells in the case of CD4+ T cells, also cytotoxicity cytotoxicity seems to play an important role." (PMID 38877590, 2024). "Within CD3+CD4+ T helper cells the following subtypes were significantly increased in patients after severe infection: effector memory T cells (EM; p = 0.009), terminally differentiated effector memory cells (TEMRA; p = 0.035), and proliferative, Ki67-expressing memory cells (p = 0.028)." (PMID 39599626, 2024). "The kinetics analysis of virus-specific CD4+ T cells exhibited that moderate and severe cases have similar peak times, which occurred around the third-week post-infection (21–22 dps), similar to previous report, and remarkably earlier than that observed in critically ill patients at 28 dps." (PMID 38811527, 2024). "Additionally, in a Th2-skewed formalin-inactivated respiratory syncytial virus (FI-RSV) vaccination model in mice, acidic HMOs were shown to reduce RSV-specific Th2 cytokine-producing CD4+ T-Cells 4- and 6-days post-infection." (PMID 39877362, 2024). "CD4:CD8 ratios below 0.5, compared to above 1.0, were independently associated with a 12-month time-lagged higher risk of ADM and infection-related malignancies (adjusted hazard ratio 2.61 [95% confidence interval {CI }1.10–6.19] and 2.03 [95% CI 1.24–3.33], respectively)." (PMID 38092042, 2024). "Interestingly, however, while spike-specific CD4+ T-cell levels among controls was similar irrespective of prior infection, dialysis patients with prior infection showed a significantly higher percentage of spike-specific CD4+ T cells than controls." (PMID 38326340, 2024). "The characteristics of natural infection were confirmed not only in terms of CD4+ TRM cell response, but also in terms of cytokine response; IFN-gamma and IL-17a responses in MV group were equal or superior to the control and DTaP vaccinated groups after challenge." (PMID 38276680, 2024). "In our study, CD4 count between 350 ~ 500 cells/μL and detectable HIV-VL were associated with lower symptoms prevalence than CD4 count > 500 cells/μL and undetectable HIV-VL among PLWH with the Omicron variant infection." (PMID 39127636, 2024). "Although the percentage of PNA+ cells, either CD4+ or CD8+, did not significantly change during T. gondii infection, PNA expression did increase as infection progressed, and at 10 dpi a significant 2- and 1.5-fold increase was observed in CD4+ and CD8+ cells, respectively." (PMID 39253089, 2024). "Recent research has demonstrated that the HLA class II presentation of Mycobacterium bacterial antigens to CD4+ cells is one of the most crucial biological steps regarding the outcome of the infection, CD8 T lymphocytes recognize bacteria exposed at the membrane of infected cells." (PMID 38694916, 2024). "Notably, infection with the CRF01_AE subtype displayed lower pre-treatment CD4+T lymphocyte counts, likely attributable to its higher CXCR4 receptor ratio." (PMID 38994006, 2024). "To determine if CPSF6 knock-out could be altering the innate immune response to infection, we assessed expression of a representative ISG, MX1, in primary CD4+ T cells from the four independent donors above at 5 days post-infection." (PMID 39678349, 2024). "As recently reported by the authors, when the infection was conducted using pseudotyped HIV incorporating the glycoprotein G from vesicular stomatitis virus (VSV-G) in a CD4/CXCR4/CCR5-independent manner, it was demonstrated that LX-2 cells exhibit permissiveness to intracellular HIV replication." (PMID 38715844, 2024).
infection (continued). "A previous study from the same group demonstrated that Ptpn22-/- mice also clear LCMV-Clone 13 infection more efficiently than Ptpn22+/+ controls, with PTPN22-deficient CD4+ T cells retaining functional capacity and being less prone to exhaustion in chronic infection." (PMID 39039893, 2024). "This work shows that an epitope-specific CD4 T cell response that expands late during MCMV infection is dramatically better at curtailing persistent replication during both natural infection and vaccination when compared to conventional memory cells that develop much earlier." (PMID 38236791, 2024). "CD200R expression on CD4+ T cells also correlated positively with infection intensity." (PMID 39250522, 2024). "To address whether our results were due to a lack of Bcl6 in bona fide DCs, we infected Clec9a.Bcl6KO mice and controls with C. rodentium and analyzed their CD4 T cell compartment on day 9 post-infection." (PMID 38688934, 2024). "We also used PBMCs, which are a more representative cell type than CD4+ T cells but have lower infection frequencies and could also show the effects of other cell types (for example, CD8+ T cells) on HIV transcription." (PMID 39163135, 2024). "GITR was identified as a crucial enhancer of CX3CR1 expression on CD4+ T cells post-infection." (PMID 39061246, 2024). "Additionally, in activated and memory CD4+ T cells, cytokine production was also reduced as a result of infection." (PMID 38932265, 2024). "Despite an accumulation of monocytes and macrophages at the site of neuronal infection in the proximity of the myenteric plexus, infection-induced injury to neurons and glia is caused principally by WNV-specific CD8+ T cells with a contribution from CD4+ T cells." (PMID 39207863, 2024). "Thus, vaccine-induced cross-reactive mucosal IgA and IgG responses or anamnestic B or CD4+ T cell responses appear insufficient to control XBB.1.5 infection in this compartment at this stage." (PMID 38337035, 2024). "When CD4+ T cell numbers are reduced, there is a subsequent reduction in the number of activated macrophages and, thus, less effective clearing of Mtb, leading to the persistence of the infection." (PMID 38543687, 2024). "To test this hypothesis, we investigated whether HIV-1 could efficiently transmit to CD4-positive T-cells from MDMs endogenously expressing MARCH8 through cell-to-cell infection." (PMID 38667313, 2024). "Levels of HIV-1 p24 similar to those detected in cells infected with viruses from SUP-T1 and CD4+ T lymphocytes (donor 1) at day 3 were observed in cells infected with viruses from CD4+ T lymphocytes (donor 2) cells and pooled monocytes only at day 5 post-infection." (PMID 38675845, 2024). "In hepatitis C virus (HCV) infection, CD4+ and CD8+ T cells are crucial for viral control." (PMID 39392861, 2024). "Moreover, zinc supplementation can reduce the incidence of infection by increasing the number of CD4+ T cells and CTLs." (PMID 38801402, 2024). "There was a trend toward increased T, NK cell frequencies among all reinfection granulomas, so we sought to identify whether prior infection promoted CD4+ or CD8+ T cell recruitment to the granuloma." (PMID 39214090, 2024). "Finally, we present two new cases in the literature of patients with recurrent infection and discuss how viewing the cases through the “lens” of CD4/CD8 ratio and IHG can facilitate clinical decisions." (PMID 39728019, 2024). "In a longitudinal analysis of the most abundant spike haplotypes in each person, rapid fluctuations in detected frequencies observed in most PWH with CD4 counts < 200 cells/μL contrasted sharply with the persistence of a single predominant haplotype throughout the course of infection in every PWOH." (PMID 39174553, 2024). "Alternatively, dynamic changes in later stages of infection–e.g., levels of inflammation, massive CD4+ T cell depletion, the onset of adaptive immunity–that change CD4+ T cell turnover and homeostasis, may limit further net increases in the RCVR." (PMID 38593120, 2024).
infection (continued). "Conversely, the percentage of TIGIT expression in CD4+ cells in the liver of WT mice was decreased for an unknown reason following infection with C. albicans, though it either increased or remained unchanged in NK and CD8+ cells, respectively." (PMID 39109867, 2024). "In addition, a decrease in Th17 cells (CD4+RORγt+), which mediate host defense mechanisms against various infections, was observed in the Citro+C1 group compared to the Citro group." (PMID 39081865, 2024). "This was followed by increases in virus-specific CD4+ T cells beginning at 4.5 days post-infection." (PMID 39575237, 2024). "During natural infection, CD8+ T cells play an important complementary role to contain the infection through their ability to eliminate already infected cells, while CD4+ helper T cells, amongst other functions, provide signals that support the development of antibody responses." (PMID 38572317, 2024). "The inability of most unadapted HIV-1 Envs to effectively mediate infection of cells expressing macaque CD4 poses a potential limitation for future applications of mmHIV-1 models, where the incorporation a variety of HIV-1 Envs with specific features of interest would be useful." (PMID 39459950, 2024). "Although mRNA vaccines induce very high binding and neutralizing antibody titers as well as CD8+ T cells and CD4+ T cells, infection may be more effective at generating better CD8+ T cell responses, critical for clearance of infected cells." (PMID 38198521, 2024). "Murine studies on Chlamydia natural history and immunity have demonstrated that only CD4+ T helper type 1 (Th1) responses (IFN-γ-mediated) are needed for clearance of initial infection and prevention of pathology, but both Th1 and antibody responses contribute to protection against reinfection." (PMID 38371301, 2024). "We have performed bulk RNA-seq experiments comparing gene expression between CD4+ T cells from acutely HIV-1–infected men and women in Zambia, because we observe lower viral load (VL) despite higher CD4+ T-cell activation in these women during acute/early infection." (PMID 39902043, 2024). "Within each risk group, where an infection was predicted to be initiated with multiple variants at a high probability, this did not correspond to a faster rate of CD4+ T cell decline." (PMID 39471873, 2024). "Another report showed, instead, that vaccination can induce a repertoire of S-specific CD4+ T-cell clones that substantially diverges from the one previously activated by the infection, thus further broadening the antigen-specific T-cell response against the virus." (PMID 39460293, 2024). "Similarly, SARS-CoV-2-specific CD4+ T-cells can be detected shortly after infection and remain detectable in up to 90% of SARS-CoV-2-infected individuals in the following months of convalescence." (PMID 39340081, 2024). "Interestingly, 85% of participants had an existing adenovirus CD4+ response even before the priming dose, which is the likely result of conserved T-cell cross-reactivity due to infection with other adenoviral types." (PMID 38603677, 2024). "We suggest that maintenance of the CD4+ T cell response post-infection may protect against future SARS-CoV-2 infections." (PMID 38812507, 2024). "In addition, Treg cell depletion during early infection minimally affected the antigen-presenting cell response but it boosted CD4+ T cell responses before the development of anti-parasite effector CD8+ T cell immunity." (PMID 38683845, 2024). "Furthermore, a H5-stalk based CD4+ T cell epitope was also identified from a natural infection study." (PMID 38805853, 2024). "When progressing into the later stages of infection, CD4+ T cells become the main produced IFN-γ." (PMID 38535532, 2024). "This significant reduction in CD4 in Mtb+/Helm+ could be explained by tissue invasion of pathogens, followed by chronic CD4 sequestration at sites of infection or increased lymphocyte apoptosis during concomitant infection." (PMID 39062045, 2024).
infection (continued). "In contrast, genuine M-tropic viruses are thought to emerge in infected patients through adaptation to body niches where macrophages or related myeloid cells are present in a context of CD4+ T cell paucity, such as in the CNS, and at the late stage of infection when the CD4 T cell count declines." (PMID 38400063, 2024). "This cohort did, however, show uniquely that an increase in CD4 T cells early in infection may help play a role in controlling the disease, as has been recently suggested." (PMID 39459926, 2024). "Both proliferating effector T cells and effector T cells already transitioning to a resting memory state (EMT CD4+ T cells) may be targets of the initial infection." (PMID 38580979, 2024). "Moreover, Flot2CD4 mice had increased TNF-α+IFN-γ+IL-2+ multifunctional CD4+ T cells, which play a crucial role in infection control." (PMID 39499901, 2024). "The limiting of autocrine IL‐2 production and the simultaneous de‐repression of IL‐2 signaling suggests that ZFP36L1 enforces dependence of CD8 T cells on paracrine IL‐2, which becomes available during the early phase of an infection and is largely produced by antigen‐specific CD4 T cells and DCs." (PMID 38039407, 2024). "Importantly, mucosal immunization of mice with unadjuvanted UV-Ct exacerbated infection via induction of FoxP3+ CD4 regulatory T cells, demonstrating that vaccine platforms and adjuvants are important considerations for effective vaccine design." (PMID 39203989, 2024). "The increased infection of U87.CD4.CCR5 cells in the IEDC co-cultures compared to IE culture reflects the enhanced basolateral release of replicative virus in the co-culture setting, underscoring the critical role of epithelial-DC interactions in amplifying mucosal viral production." (PMID 39729509, 2024). "CD4+ T cell numbers were quantified in these tissues at 6 weeks and 3 months post-infection." (PMID 39588838, 2024). "A second surprising finding was that while Tregs were present as expected from earlier T. congolense studies, they did not have an IL-10 regulatory signature, and the proportion of these cells in the total CD4+ T cell pool drastically decreased during the chronic stage of infection." (PMID 38535532, 2024). "Following HTLV-1 infection, PVL was detected in peripheral blood two weeks post-infection, and at five weeks post-infection Tax was found to be significantly elevated in the spleen and CNS, peaking at 14 weeks post-infection and overrepresented in CD4+ T cells." (PMID 39459949, 2024). "Moreover, breakthrough infections were more frequent among previously uninfected individuals, who had significantly lower vaccine-induced neutralizing antibodies and CD4 T cell levels." (PMID 38594497, 2024). "However, because these cytokines can also cause tissue damage if over-produced, regulatory immune responses develop, and the balance between pro-inflammatory and regulatory CD4+ T cells responses determines the outcomes of infection." (PMID 38881737, 2024). "Next, our model framework revealed we would not expect to observe a positive association between multiple variant infections and faster CD4+ T cell decline, in the absence of an explicit dependency." (PMID 39471873, 2024). "First, to define the kinetics of CD4+ T cell dependency during acute infection in more detail, we transiently depleted CD4+ T cells at selected time points post-infection in C57BL/6 mice (depletion start: day -4, 0, 3, 6, 7, 8, 9, 12, 15, 18 pi) and analyzed NrHV viremia over time." (PMID 39392861, 2024). "One individual had very high DPB4/S167+ CD4+ T cells early post infection." (PMID 39284068, 2024).